APOE (apolipoprotein E)
Diseases named in the same sentence as APOE in open-access papers (continued):
Sharing a sentence is not in itself a finding about the gene and the disease.
esophageal cancer (4 papers, 2022 to 2023). A primary or metastatic malignant neoplasm involving the esophagus. "Furthermore, APOE, which is essential in the development of cardiovascular and neurodegenerative diseases, had a nominally positive association (P < 0.05) with esophageal cancer and hematological malignancy." (PMID 36797296, 2023).
fungal infections (4 papers, 2020 to 2024). "This is in line with previous studies from our labs and others revealing impaired dendritic cell migration and T-cell egress via lymphatics in ApoE−/− mice as well as higher susceptibility to bacterial, viral or fungal infections in these mice." (PMID 36685213, 2022). "In addition, in vivo studies have revealed that apoE is a protein with anti-inflammatory and anti-infective properties, showing that apoE-deficient mice exhibited an increased susceptibility in response to Gram-negative or fungal infection." (PMID 34019903, 2021).
glomerulonephritis (4 papers, 2010 to 2025). A renal disorder characterized by damage in the glomeruli. "Immunocytochemical staining of renal biopsy specimens featuring various types of glomerulonephritis showed deposition of ApoE and ApoB in mesangium, sclerosed areas of glomeruli, and glomerular cells." (PMID 33633132, 2021).
Granuloma (4 papers, 2015 to 2024). A compact, organized collection of mature mononuclear phagocytes, which may be but is not necessarily accompanied by accessory features such as necrosis. "In conclusion, future studies are needed to define macrophage subtypes, and involvement of matrix metalloproteinases along with ApoE, in patients with chronic non resolving granulomas and those whose disease has resolved." (PMID 34681679, 2021). "By contrast, among the animals receiving ND treatment for 4 or 12 weeks, the ApoE−/− mice displayed a minimal number of inflammatory cells in the peribronchiolar and perivascular sites, and very few granulomas developed at 24 weeks of ND." (PMID 25975841, 2015). "Our experiments document novel differences between the transcriptomes of FCMs and NFMs obtained from subcutaneous sponge-induced granulomas in living ApoE null mice." (PMID 26197235, 2015). "We hypothesized that at 60 days, high levels of ApoE in Mmp12 KO mice instilled with MWCNT might coincide with granuloma resolution." (PMID 34681679, 2021). "Based on these observations, we hypothesized that ApoE might also play a role in transforming the Mmp12 KO macrophage phenotype into a form responsible for granuloma resolution." (PMID 34681679, 2021). "Widely distributed granulomas were observed in the ApoE−/− mice following WD for 24 weeks." (PMID 25975841, 2015). "Correspondingly, ApoE expression is increased in MWCNT-instilled Mmp12 KO mice at 60 days, when granulomas are resolving." (PMID 34681679, 2021). "The relationship between ApoE and granuloma resolution is not clear." (PMID 34681679, 2021).
herpes labialis (4 papers, 2010 to 2022). A lesion caused by type 1 or type 2 herpes simplex virus, typically involving the oralfacial region. "A concurrent finding was that APOE-ε4 is a risk for herpes labialis (cold sores), which is usually caused by the virus in the peripheral nervous system." (PMID 39483362, 2022). "Our finding that in the peripheral nervous system, APOE-ε4 is a major risk factor for cold sores (herpes labialis) provided strong indirect support for this conclusion." (PMID 34205498, 2021). "Further, the finding that APOE-ε4 is a risk for herpes labialis in the PNS—caused usually by HSV1—is consistent with the concept that HSV1 in APOE-ε4 carriers is particularly damaging in the nervous system." (PMID 34205498, 2021). "The present author had planned to seek a possible APOE-SARS-CoV2 link, because studies by her lab had revealed that APOE genotype determines susceptibility to a pathogen, or severity of damage by the pathogen, in a number of infectious diseases, including herpes labialis." (PMID 34205498, 2021).
HIV-1 infection (4 papers, 2018 to 2022). The type species of lentivirus and the etiologic agent of acquired immunodeficiency syndrome (AIDS). "First, the microarray analysis revealed that HIV-1 infection up-regulated the expression of ApoE in MDMs at 3 days post-infection (dpi)." (PMID 30496280, 2018). "Further, of the three known human isoforms of ApoE, ApoE4 enhances HIV-1 infection and accelerates HIV-1 disease progression." (PMID 29558961, 2018). "Of the three known human isoforms of ApoE, ApoE4 enhances HIV-1 infection and accelerates HIV-1 disease progression." (PMID 29558961, 2018). "It will be also necessary to clarify to what extent ApoE plays its inhibitory role in HIV-1 infection among donors because the basal expression level of ApoE in macrophages varied among donors." (PMID 30496280, 2018). "This was further confirmed at the protein levels by western blot: HIV-1 infection significantly up-regulated endogenous ApoE expression in all 3 donors tested." (PMID 30496280, 2018). "In this study, we initially found that HIV-1 infection selectively up-regulated ApoE in human monocyte-derived macrophages (MDMs)." (PMID 30496280, 2018). "In this study, we initially investigated the effect of HIV-1 infection on endogenous ApoE expression in MDMs by using the JR-FL strain of HIV-1." (PMID 30496280, 2018). "In the present study, we found that the expression of APOE was increased in non-infected cells compared to that in latently infected and productively infected cells, and knockdown of APOE promoted HIV-1 infection in T cells by interfering with viral RT or integration." (PMID 33504604, 2021). "Apolipoprotein E (APOE) is involved in lipoprotein metabolism and is reported to inhibit HIV-1 infection in macrophages." (PMID 33504604, 2021). "Regarding the relationship between APOE and HIV infectivity, one report showed that the APOE E4 isoform protein enhances HIV-1 infection." (PMID 33504604, 2021). "However, when MDMs were incubated with the supernatants of HEK293A cells transfected with the empty vector (see “Mock”), ApoE induction was never detected even when monitored up to day 8, confirming that the observed change in ApoE levels was caused by HIV-1 infection." (PMID 30496280, 2018). "Even though latently infected cells showed a very similar transcriptomic profile to that of non-infected cells, we found that SPP1 and APOE were significantly enriched in non-infected cells compared to that in latently infected cells and that knock down of these genes promoted HIV-1 infection." (PMID 33504604, 2021). "The reason for this discrepancy regarding the role of ApoE in HIV-1 infection is not clear yet." (PMID 30496280, 2018). "However, it has not been explored whether ApoE functions as a stimulator or an inhibitor of HIV-1 infection in MDMs." (PMID 30496280, 2018). "The results showed that mRNA levels of already known host restriction factors which inhibit HIV-1 infection, TRIM5α, MX2, SAMHD1, SERINC3, SERINC5, IFITM2, IFITM3, ApoE, and PSGL-1 were not significantly elevated by γ-IFN." (PMID 35883685, 2022). "Although we did not determine the extent to which ApoE-HDL affects HIV-1 infection, our finding seems contradict with a previous report that non-lipidated ApoE4 at 10 μg/ml enhances HIV-1 infection in vitro." (PMID 29558961, 2018).
hyperandrogenemia (4 papers, 2021 to 2025). "When stratified according to demographic parameters, hyperandrogenemia showed increased APCS, ApoE and ApoA1, whereas PAPPA was decreased." (PMID 38256230, 2024). "There was a difference when stratifying according to hyperandrogenemia, with APCS, ApoE and ApoA1 higher in hyperandrogenemia (p < 0.01, p < 0.04 and p < 0.01, respectively), while PAPPA was decreased in hyperandrogenemia (p < 0.01)." (PMID 38256230, 2024). "Patients with hyperandrogenism+oligo/anovulation+polycystic ovaries (PCO) or hyperandrogenism+PCO had lower total ApoE-containing and ApoE-poor HDL-PAF-AH activities, while those with oligo/anovulation+PCO showed decreased total and ApoE-poor HDL-PAF-AH activities, compared to the control women." (PMID 34281251, 2021).
hypercoagulability (4 papers, 2013 to 2025). "Despite that we show a significant association between hypercoagulability and high rate of spontaneous mortality in TMPro/Pro:ApoE−/− mice, further studies are needed to precisely determine the underlying cause of this observation." (PMID 23409043, 2013). "Evaluating ApoE genotype, particularly distinguishing ApoE ε3 from ApoE ε4 carriers, could therefore add value to traditional thrombophilia screening, especially in complex or unexplained thrombotic cases." (PMID 41465167, 2025). "The aim is to show how ApoE genotyping, when considered together with endothelial biomarkers, may help overcome the limits of traditional thrombophilia testing." (PMID 41465167, 2025). "One of the principal advantages of integrating APOE genotyping and endothelial biomarker evaluation into a screening framework lies in the potential to reduce the over-utilization of non-informative thrombophilia testing." (PMID 41465167, 2025). "Moreover, APOE genotyping may be particularly informative in patients with thrombotic events despite negative results on conventional thrombophilia panels." (PMID 41465167, 2025).
inclusion body myositis (4 papers, 2015 to 2022). A slowly progressive degenerative inflammatory disorder of skeletal muscles characterized by late onset weakness of specific muscles and distinctive histopathological features. "Indeed, western blotting for cellular APOE, which has been found to abnormally accumulate in inclusion body myositis, showed a readily detectable increase as early as 6 months and remained elevated throughout the later time points." (PMID 29666155, 2018). "The accumulation within abnormal muscle fibers of several pathologic and Alzheimer-related proteins such as beta-amyloid precursor protein (beta-APP), phosphorylated tau, alpha-1-antichymotrypsin, apolipoprotein E and presenilin-1 is an unusual feature of sporadic inclusion-body myositis (sIBM)." (PMID 28407771, 2017).
iron overload (4 papers, 2016 to 2025). "ABCA1 mutation in humans results in Tangier Disease, which is characterized by low levels of ApoE and HDL in both the brain and plasma." (PMID 30373276, 2018).
liver dysfunction (4 papers, 2018 to 2022). "Taken together, these findings show that loss of Dscr-1 specifically suppresses lipid resorption into the aortic endothelium, resulting in synergistically increased cholesterol levels in peripheral tissue in combination with ApoE−/− and Dscr-1−/−-mediated severe liver dysfunction." (PMID 33895138, 2021).
lupus nephritis (4 papers, 2017 to 2025). Glomerulonephritis in the context of systemic lupus erythematosus. "A study combining scRNA-seq and spatial transcriptomics of lupus nephritis (LN) detected apolipoprotein E (APOE)+ monocytes as a specific monocyte population in LN kidney tissue." (PMID 39980019, 2025).
lymphedema (4 papers, 2021 to 2024). Excess fluid collection in tissues, causing swelling. "In addition, the change of APOE level was earlier than that of the lymphedema index." (PMID 34873574, 2021).
male infertility (4 papers, 2021 to 2024). The inability of the male to effect fertilization of an ovum after a specified period of unprotected intercourse. "Specifically, the lower fertility potential of specific genotypes accompanied by the decrease in APOE concentration suggests an association with male infertility." (PMID 37048090, 2023). "The impact of APOE on male infertility was extensively studied on different genotypes and its potential impact on steroidogenesis has been investigated." (PMID 37048090, 2023).
mastitis (4 papers, 2020 to 2025). Inflammation of breast tissue during lactation or postpartum due to an obstructed duct or infection. "Still, a number of the proteins, for instance, apolipoprotein E and serotransferrin-like protein, have been more strongly associated with colostrum and, at the same time, mastitis, although they are also present in normal (uninfected) milk." (PMID 37889706, 2023). "Concurrently, elevated expression of the apoptosis-related genes caspase-8 (cas8) and APOE activates apoptotic pathways, while the activation of metabolic pathways collectively drives the onset and progression of mastitis." (PMID 41305370, 2025). "This points strongly to their direct role in immunity and inflammation, as has been suggested, even though there was also a report of apolipoprotein E decreasing during mastitis, which contradicts our findings in the present study." (PMID 37889706, 2023). "However, we found that APOA1, APOA4, APOE, and RBP4 were downregulated during clinical mastitis." (PMID 36335251, 2022).
memory (4 papers, 2020 to 2025). The activities involved in the mental information processing system that receives (registers), modifies, stores, and retrieves informational stimuli. "Memory deficits were also observed in APOE4 knock-in mice, in which the APOE gene is replaced by knocking in the human ε4 allele." (PMID 33488358, 2020).
Neurofibrillary tangles (4 papers, 2015 to 2025). Pathological protein aggregates formed by hyperphosphorylation of a microtubule-associated protein known as tau, causing it to aggregate in an insoluble form. "Correspondingly, females with ApoE ε4 allele were found to have greater Aβ and neurofibrillary tangle in autopsy cases and higher CSF levels of tau in healthy elderly adults." (PMID 26538817, 2015).
osteoarthritis (4 papers, 2018 to 2025). A noninflammatory degenerative joint disease occurring chiefly in older persons, characterized by degeneration of the articular cartilage, hypertrophy of bone at the margins and changes in the synovial membrane. "Elevated APOE expression in fibroblasts and macrophages promotes cartilage degeneration in osteoarthritis (OA), while APOE inhibition alleviates OA progression." (PMID 40612951, 2025). "Cold exposure is shown to aggravate osteoarthritis (OA) by suppressing chondrocyte APOE, triggering lipid accumulation, mitochondrial dysfunction, and apoptosis." (PMID 40664892, 2025). "Nevertheless, RGX-104 serves as a compensatory therapeutic strategy by reactivating cold-diminished APOE expression in chondrocytes, thereby mitigating cold-aggravated osteoarthritis pathology." (PMID 40664892, 2025). "Specifically, APOE-dependent lipid efflux mitigates osteoarthritis progression, highlighting lipid metabolism regulators as safer candidates." (PMID 40664892, 2025). "Collectively, these findings demonstrate that low-temperature exposure exacerbates osteoarthritis progression by downregulating APOE expression, inducing lipid accumulation in chondrocytes, which subsequently drives mitochondrial dysfunction and potentiates apoptotic pathways." (PMID 40664892, 2025). "In addition, APOE, which primarily participates in cholesterol metabolism and transport, may consequently play a role in the onset of cholesterol-induced osteoarthritis." (PMID 37853066, 2023).
renal fibrosis (4 papers, 2015 to 2022). A final common manifestation of a wide variety of chronic kidney diseases characterized by glomerulosclerosis and tubulointerstitial fibrosis. "Phospho-Smad levels (TGF-β downstream signaling) were increased in obese ApoE-/- mice, which was associated with increased renal fibrosis in these mice." (PMID 25803585, 2015). "Compared with the sham group, the 5/6 Nx ApoE–/– mice exhibited a significant increase in the macrophage infiltration of the kidneys (nephritis), upregulation of IL-1β, generation of reactive oxygen species, reduced creatinine clearance, and renal fibrosis." (PMID 36552668, 2022).
scrapie (4 papers, 2012 to 2025). A fatal disease of the nervous system in sheep and goats, characterized by pruritus, debility, and locomotor incoordination. "We showed here that infection of wild type mice with 22L mouse adapted scrapie strain is associated with significant increase in the total brain apoE protein and mRNA levels and also with a conspicuous cell-type shift in the apoE expression." (PMID 34565486, 2021). "By infecting APOE-TR mice with 22L mouse adapted scrapie strain, we identified a differential effect of human APOE alleles on prion induced neurodegeneration." (PMID 41282061, 2025). "Male and female ε2/ε2, ε3/ε3, and ε4/ε4 APOE-TR mice were inoculated with 22L mouse-adapted scrapie strain or normal brain homogenate and monitored with behavioral testing from 10-week post inoculation (wpi)." (PMID 41282061, 2025). "We first compared the total brain apoE level and its expression by astrocytes and microglia in wild-type (WT) B6 mice, which were intraperitoneally inoculated with 22L mouse adapted scrapie strain or NBH." (PMID 34565486, 2021). "Apolipoprotein E and peroxiredoxin 6 (PRDX6) were identified as upregulated proteins in brains of scrapie-infected mice and cultured neuronal cell lines." (PMID 23210548, 2012). "We reexamined here the role of apoE in prion pathogenesis and contrary to this past report found that absence of apoE modestly, yet statistically significantly shortens incubation time of Apoe−/− mice inoculated with the two distinct mouse adapted scrapie strains 22L and ME7." (PMID 34565486, 2021).
skin cancer (4 papers, 2014 to 2024). "Our results identify the complexity of known pleiotropic genes such as APOE, and suggest a new causal role for TGM3 in skin cancer." (PMID 38997278, 2024). "Additionally, the findings suggest that the SKH-hr2 and SKH-hr2+ApoE models are particularly well suited for investigating the pathophysiology of cSCC and testing novel therapeutic interventions, making them promising tools for advancing skin cancer treatment." (PMID 39456640, 2024). "This could suggest a pivotal role of the ApoE protein in the regulation of proteasome activity in tumors; ApoE deficiency may not allow the enhancement of proteasome activities in the skin tumors of these animals." (PMID 39456640, 2024). "The observed clinical manifestations of squamous cell carcinoma in the SKH-hr2+ApoE and SKH-hr2 murine models present significant insights into the complexity of skin cancer development under the influence of genetic and UV radiation factors." (PMID 39456640, 2024).
spinal muscular atrophy (4 papers, 2018 to 2023). A motor neuron disease that affect the muscles, and characterized by muscle weakness and atrophy resulting from progressive degeneration and irreversible loss of the anterior horn cells in the spinal cord (i.e., lower motor neurons) and the brain stem nuclei. "Another study demonstrated that a derivative of an ApoE could induce a 0.25-fold increase in exon 7 inclusion in the pre-mRNA of the spinal cord and, to a lesser extent, in the brain of a spinal muscular atrophy mouse model, improving the diseased mice’s phenotype." (PMID 37830609, 2023).
systemic amyloidosis (4 papers, 2018 to 2021). "Both apoE and CLU are representative signature proteins in various types of systemic amyloidosis." (PMID 30691533, 2019).
thoracic aortic aneurysm (4 papers, 2013 to 2022). An aneurysm formed in the wall of the proximal portion of the descending aorta proceeding from the arch of the aorta. "Subcutaneous infusion of AngII for 2 weeks produced AAAs in 92% and thoracic aortic aneurysms (TAAs) in 42% of apoE−/− mice, whereas no animals infused with saline developed AAA." (PMID 23537804, 2013).
vitamin B12 deficiency (4 papers, 2020 to 2025). A disease characterized by low serum levels of vitamin B12, either inherited or acquired. "Given that B12 is a key regulator of homocysteine concentrations, these findings are particularly concerning as vitamin B12 deficiency is widespread in older adults and an estimated 25% of the global population carries the ApoE ε4 allele." (PMID 40717068, 2025). "The APOE ε4 allele does not affect the biomarker concentrations while plasma vitamin B12 deficiency is associated with higher plasma t-Tau concentrations." (PMID 33183357, 2020).